PDGFRB (platelet derived growth factor receptor beta)
Diseases named in the same sentence as PDGFRB in open-access papers (continued):
Sharing a sentence is not in itself a finding about the gene and the disease.
tumor (continued). "Several studies underscore the critical role of PDGFRβ in regulating angiogenesis and establishing a tumor microenvironment that propels the progression of metastatic GC." (PMID 40282535, 2025). "PDGF-CC, PDGF-DD, and PDGFRα were predominantly expressed in tumor cells, whereas PDGFRβ was localized primarily to the vascular stroma." (PMID 40508013, 2025). "In two individual patients with paired tumor samples, immunoblot analysis revealed an increase in pEGFR and PDGFRβ in both post- versus pre-BRAFi pairs." (PMID 40900823, 2025). "Meanwhile in NSD tumours, EGFR mutations and copy number gains, in addition to the gains of additional growth factor receptor genes PDGFRB and FGFR4, suggest that this pathway is activated via a different mechanism." (PMID 41509216, 2025). "PDGFRB signaling in the tumor microenvironment promotes epithelial-mesenchymal transition (EMT) and is inhibited by BRCA1, making it a significant therapeutic target, particularly in BRCA1-deficient TNBC." (PMID 41017855, 2025). "Inaddition, the PET data indicated that the accumulation of[68Ga]Ga-DOTA-ZTRI correlated directly with PDGFRβ expressionby tumor cells; therefore, the drug actively accumulated inPDGFRβ-positive HCC cells in laboratory animals." (PMID 41479565, 2025). "In ALK-negative tumours, alternative drivers have been identified, including ROS1, RET, NTRK3 and PDGFRB rearrangements or mutations." (PMID 40980125, 2025). "AGASAC frequently expressed PDGFRβ in a high percentage of neoplastic cells and in tumor stromal compartments with high intensity, supporting the addition of TKIs to AGASAC treatment, especially in tubular tumors." (PMID 41472102, 2025). "PDGFRB exhibited differential expression across most tumor types in TCGA, indicating a correlation with poor survival outcomes." (PMID 40128057, 2025). "The simultaneous inhibition of EphB4 and PDGFRβ by dasatinib resulted in a significant decrease in cell viability and tumor growth rate and significantly prolonged survival in vivo." (PMID 40508013, 2025). "In in vivo experiments, silencing SRSF3 significantly decreased tumor development and progression, likely by affecting the platelet-derived growth factor receptor beta (PDGFRB) pathway, which plays a critical role in tumor growth and angiogenesis." (PMID 39915450, 2025). "Platelet-derived growth factor receptor beta expression correlated with tumor grade (r = 0.286; P = .021), venous tumor thrombosis (r = 0.263; P = .034), M+ category (r = 0.305; P = .014), and adrenal metastases (r = 0.306; P = .041)." (PMID 40434293, 2025). "The hyperactivation of this receptor facilitates neovascularization and enhances the survival of malignant cells, rendering PDGFRβ a highly promising therapeutic target for both inhibiting tumor growth and increasing sensitivity to systemic treatments." (PMID 40282535, 2025). "In conclusion, the expression of the tyrosine kinase receptors PDGFRα and, to a somewhat lesser extent, PDGFRβ, was detected on the surface and in the cytoplasm of primary tumor cells of patients with RCC stage pT1a-T4N0/+M0/+." (PMID 40434293, 2025). "PDGFRB signaling drives smooth muscle cells and pericytes to newly created blood vessels, which aids in angiogenesis and encourages tumor growth by promoting cell survival and proliferation." (PMID 40429793, 2025). "For instance, the fusion of PDGFRβ‐specific affibody ZPDGFRβ with ABD‐TRAIL has been demonstrated to effectively target tumor cells and PDGFRβ‐positive pericytes on tumor microvessels, facilitating the homing of TRAIL to the tumor site." (PMID 39740038, 2025). "Differential expression of PDGFRB in standard, tumor, and different clinical stage samples was calculated using R software (version 3.6.4)." (PMID 40128057, 2025). "Excessive activation of PDGF receptor beta (PDGFRβ) signaling induces autocrine stimulation of tumor cell growth and tumor angiogenesis." (PMID 41375037, 2025).
tumor (continued). "This study analyzes PDGFRB in relation to tumor stemness, providing insights not only into prognosis but also evaluating the potential of PDGFRB as a marker for tumor stem cells." (PMID 40128057, 2025). "In some cases, SMA and PDGFRB staining was focal, localized to the mural layer of small blood vessels penetrating tumor nests." (PMID 40841830, 2025). "PDGFRβ signaling is essential in tumor angiogenesis, as genetic studies have detected PDGFRB expression in hyperplastic blood vessels and tumor microvasculature." (PMID 40332008, 2025). "Four primary cell populations were first identified using canonical cell markers: WT tumor cells (WT1, NCAM1, SIX1, SIX2, PAX2), cancer-associated fibroblasts (CAFs) (ACTA2, TAGLN, COL1A1, PDGFRB), endothelial cells (PECAM1, CLDN5, ENG, VWF) and immune cells." (PMID 40098972, 2025). "In the CD group, PDGFRβ, a key factor in tumor growth, survival, and angiogenesis, after an initial increase at T3, decreased significantly at T9 to later increase significantly at TTP (p < 0.05)." (PMID 40282535, 2025). "When the cancer metastasized, it usually formed more solid tumors with the same or lower levels of PDGFRβ compared to the original tumor." (PMID 41472102, 2025). "PDGFRβ upregulates P-gp expression, contributing to chemoresistance and the tumour’s protection against therapeutic interventions." (PMID 40282535, 2025). "GBM cells are distinguished by the presence of PDGFRs, specifically PDGFRα and PDGFRβ, which are overexpressed and persistently active in this type of tumor." (PMID 40332008, 2025). "PDGF signals through two Class III cell-surface tyrosine kinase receptors, PDGFRα and PDGFRβ, to regulate tumor angiogenesis." (PMID 38672182, 2024). "While TCM from untreated BC cells induced increased expression of VEGFR2, VEGFA, FGFR1, HIF-1α and PDGFRB, this effect was significantly inhibited by the muscone administration to tumor cells prior to isolation of the 231TCM and 549TCM." (PMID 38898449, 2024). "In clear cell renal cell carcinoma, inactive von Hippel-Lindau (VHL) induces histone lactylation in a HIFs-dependent manner, thereby transcriptionally activating the expression of platelet-derived growth factor receptor β (PDGFRβ) to promote tumor progress." (PMID 38200523, 2024). "A trend of decreased mOS was observed in relation to Cyclin D1 overexpression and normal expression, with mOS of 20.09 vs. 33.23; p = 0.056, while high PDGFRβ expression in the tumor stroma resulted in survival rates of 24.90 vs. 48.36 months; p = 0.068." (PMID 38791897, 2024). "Studies have shown that PDGFRB plays an essential role in the regulation of tumor proliferation, apoptosis, differentiation, drug resistance, and invasion." (PMID 38778089, 2024). "Even in cancer, ECs release PDGF-B that induces pericyte recruitment in the growing tumor vasculature by activating PDGFRβ signaling." (PMID 39086395, 2024). "We also examined the impact of the deletion of PDGFRβ on hepatic fibrosis and tumor formation in the current diabetic MASH model." (PMID 39394459, 2024). "High expression of PDGFRβ and PDFGRα in the tumor stroma characterized 90% (19/21) and 86% (18/21) of the tumors, respectively." (PMID 38791897, 2024). "Encouraged by these studies, continued efforts are expected in the upcoming years, addressing the role of PDGFRβ as a biomarker in tumor collections derived from radioimmunotherapy trials." (PMID 38980580, 2024). "We investigated the impact of the PDGFRβ deletion on tumor progression in dMASH by analyzing 20-week-old FL and KO mice." (PMID 39394459, 2024). "The approach of suicide gene–mediated depletion of PDGFRβ-positive pericytes has been used to analyze the impact of PDGFRβ-positive pericytes on tumor metastasis." (PMID 38980580, 2024).
tumor (continued). "High expression of PDGFRβ and PDGFRα in the tumor stroma was observed in 83% (205/248) and 74% (183/248), respectively." (PMID 38791897, 2024). "In vivo experiments utilizing the experimental inhibition of PDGFRB via imatinib resulted in reduced tumour growth and increased apoptosis in a rat model of CCA." (PMID 38877653, 2024). "Anlotinib is a multiple TKI that targets VEGFR2 and PDGFRβ and therefore exhibits broad‐spectrum anti‐tumor activity." (PMID 39618078, 2024). "Imatinib mesylate (STI571), is a selective kinase inhibitor that inhibits the activation of ALB, KIT, PDGFRA, and PDGFRB, thereby inhibiting tumor growth." (PMID 39600645, 2024). "Studies have confirmed that inhibiting the anoikis of GC cells can activate signaling pathways like JAK-STAT3, PI3K/AKT and PDGFB/PDGFRβ, thereby leading to epithelial–mesenchymal transition in tumor cells, and then induce tumor proliferation and metastasis." (PMID 39329635, 2024). "While primary tumor growth in in vivo models is reduced with pericyte ablation, the number of circulating tumor cells and lung metastasis is greatly enhanced after PDGFRβ+ cell depletion." (PMID 39086395, 2024). "In terms of CNS tumors, some studies have identified tumor-associated stromal cells expressing CAF markers in GB and have discovered protumoral effects of αSMA- or platelet-derived growth factor receptor-beta-positive fibroblasts." (PMID 39186169, 2024). "Univariate and multivariate survival analysis according to tumor characteristics and combined expression of platelet-derived growth factor receptor beta (PDGFRb), periostin and α-smooth muscle actin (α-SMA)." (PMID 38328551, 2024). "PDGFRβ, receptor tyrosine kinase, is overexpressed in various cancers and plays an important role in tumor progression, making it a potential therapeutic target." (PMID 39473823, 2024). "Five genes were subsequently selected by LASSO regression; CGB5, THPO, and PDGFRB were upregulated in the tumor tissue, while SLC10A2 and APOD were downregulated." (PMID 38228846, 2024). "The study suggests that the aptamers alone have therapeutic potential, as Gint4.T notably inhibits the proliferation and migration of tumor cells by binding to PDGFRβ, inhibiting its activity and subsequent effects." (PMID 38675202, 2024). "Specifically, FGF-2 is a potent pericyte-stimulating factor; by binding to FGFR2, it induces pericyte proliferation and orchestrates PDGFRβ signaling for vascular recruitment, as demonstrated in the tumor context." (PMID 39086395, 2024). "SULF2 is upregulated in human CCA and is associated with enhanced PDGFRβ-YAP signalling, tumour progression and chemoresistance." (PMID 38332153, 2024). "Alternatively, small molecule inhibitor against both PDGFR⍺ and PDGFRβ, CP-673,451, inhibits tumour growth by inducing terminal differentiation of GBM cells into neural-like cells." (PMID 38615034, 2024). "Anlotinib is an oral TKI that targets multiple kinases such as VEGFR2, fibroblast growth factor receptors (FGFR1‐3), PDGFRβ and c‐Kit and can effectively inhibit tumor growth and vasculature." (PMID 39618078, 2024). "Kuzmanov A and his partners pointed out that pharmacological inhibition of PDGFBB/PDGFRβ signaling reduced vessel functionality, tumor growth and cell migration and invasion during breast carcinogenesis." (PMID 38378786, 2024). "Immunohistochemistry assessed PDGFD and PDGFRB expression, while multicolor immunofluorescence and flow cytometry provided insight into spatial relationships and the tumor immune microenvironment." (PMID 38652223, 2024). "The tumor-inhibiting efficacy of the compound was indeed restricted to models expressing both high PDGFB as well as high stromal PDGFRβ levels, highlighting the importance of improved knowledge on active tumoral PDGF signaling for future clinical applications." (PMID 38980580, 2024). "Most of anlotinib’s targets were upregulated in DDLPS, while FGFR1, PDGFRA and PDGFRB were significantly upregulated in tumor tissues." (PMID 39117615, 2024).
tumor (continued). "In TNBC, PDGFRβ plays a notable role in mediating endothelial cell differentiation and vasculogenic mimicry in tumor cells." (PMID 38699644, 2024). "Treatment with PKI-587 and imatinib mesylate effectively inhibited the phosphorylation of Akt and mTOR in PDX tumours, and imatinib inhibited PDGFRB phosphorylation." (PMID 36522480, 2023). "Existing drug studies targeting PDGFRβ have shown that reducing the expression of PDGFRβ in cells can inhibit tumor progression." (PMID 38027998, 2023). "The tumor growth rate in mice with PDGFRβ-overexpressing TNBC cells was significantly faster than that in the control cell group." (PMID 38027998, 2023). "Immunohistochemistry analysis of metastatic nodules demonstrated marked mitigation of the FAP+, α‐SMA+, DESMIN+, PDGFRα+, and PDGFRβ+ fibrotic components in TGF‐βR1‐treated Bmal1−/− tumor‐bearing mice." (PMID 37330661, 2023). "Both tumor and fibroblast expression of PDGFRα and PDGFRβ was significantly correlated in pre-treatment and relapse samples and high post-treatment tumor and fibroblast PDGFRβ levels were associated with a short time to treatment failure (TTF)." (PMID 36909339, 2023). "The fusion vector increased DNA internalization only in PDGFRβ-positive cells, indicating targeted gene delivery of the H2A-YG2 vector to PDGFRβ-positive tumor stromal cells." (PMID 37242744, 2023). "PET imaging of mice bearing PDGFRβ+ colorectal xenografts with 89Zr produced high-contrast tumor images with clean liver background, which greatly triggered our interest to evaluate the potential of PDGFRβ-targeted imaging for HCC diagnosis." (PMID 37256321, 2023). "In summary, Ezetimibe exhibits a significant in vivo anti-tumor effect and exerts this effect by inhibiting the PDGFRβ/AKT pathway." (PMID 38027998, 2023). "We demonstrated that PDAC cells secrete EZR‐rich sEVs to induce α‐SMA and PDGFRB expression in fibroblasts, exacerbating tumor progression and metastasis in PDAC." (PMID 37171030, 2023). "The increased tumor angiogenesis in this model is related to enhanced endothelial Vegf receptor 1, 2, and 3; platelet-derived growth factor receptor beta (Pdgfrβ); platelet-derived growth factor subunit B (Pdgfb); and tyrosinkinase KIT (c-kit) expression." (PMID 35954274, 2022). "Phosphorylation and activation of STAT3 in myofibroblasts is downstream of platelet derived growth factor receptor β (PDGFRβ), an established and key regulator of the TME, linked to tumour growth." (PMID 36589727, 2022). "Altogether, these results demonstrate that PDGFRβ expression facilitates ALK+ tumor formation and dissemination, and that our generated genetic mouse model is a valid tool to study the effects of PDGFRβ in ALK+ ALCL pathogenesis." (PMID 36045346, 2022). "Apatinib can effectively inhibit the kinase activity of VEGFR-2, c-kit and c-src, and inhibit the phosphorylation of VEGFR-2, c-kit and PDGFRβ to inhibit tumor growth, reduce microvessel density and promote tumor cell apoptosis in mice." (PMID 36316341, 2022). "Immunohistochemical results showed that the expression levels of CD31, PDGFB, VEGF, VWF, and PDGFRB in the HCC-PDX tumor tissues were all downregulated by MTE in a dose-dependent manner." (PMID 35847002, 2022). "The same situation happens to a type III PDGFRβ kinase inhibitor, tandutinib, which can only be used to inhibit the expression of PDGFR in tumor stroma." (PMID 36254250, 2022). "The activation of PDGFRB on tumour cells stimulates proliferation, invasion and can induce epithelial-to-mesenchymal transition (EMT)." (PMID 36139509, 2022). "Exogenous PDGF-D has been identified to up-regulate tumor PDGFRβ expression in tongue squamous cell carcinoma, which promotes EMT through P38/AKT/ERK pathway." (PMID 35659308, 2022). "The activation of the PDGFRβ/STAT5 axis in tumor cells results in a malignant boost by increasing autocrine-dependent proliferation and evading apoptosis." (PMID 36045346, 2022).
tumor (continued). "This work presents an alternative mechanism for the significant involvement of PDGFRβ in tumor progression." (PMID 35637958, 2022). "Summing up our findings, we certified the activation/overexpression of PDGFRβ on mononuclear stromal/tumor cells at protein level (paraffin sections) as an effect of denosumab treatment." (PMID 36091939, 2022). "We selected 118 S100P-SPP1 + iCCApps from our TMA cohort to explore the prognostic values of ID3 + tumor cells and PDGFRβ + stromal cells (most of which were CAFs)." (PMID 35347134, 2022). "Combining tumor-normal and inter-tumor analyses, we identified overexpressed targets including PDGFRB, FGFR4, ERBB2/3, CDK6 kinases and MFAP5, HMCN1, and Hsp proteins in HCC, many of which showed low frequencies of genomic and/or transcriptomic aberrations." (PMID 35433463, 2022). "Our results confirm (for the first time) the activation of PDGFRβ on mononuclear stromal/tumor cells at protein level as an effect of denosumab treatment, which has so far only been demonstrated by phosphoprotein array analysis (protein lysates)." (PMID 36091939, 2022). "As a single gene, the expression of PDGFRB performed remarkably well in predicting CMS4 status in the original composite cohort of 3232 primary tumours (AUROC = 0.86; 95% CI: 0.85−0.88)." (PMID 36139509, 2022). "Evidence suggests that the tumour cells and the macrophages in the tumour microenvironment induce PDGFRβ expression on adjacent fibroblasts and upregulate PDGFRβ activity in a paracrine fashion promoting PDGF-mediated fibrogenesis." (PMID 35554845, 2022). "The fact, that the intensity of PDGFRβ immunostaining in tumor cells was decreased in recurrences after denosumab treatment confirms the causing role of denosumab regarding PDGFRβ overexpression however, the precise mechanism is not known." (PMID 36091939, 2022). "There was a significant positive correlation between increasing tissue stiffness in tumor stroma and SMAα and PDGFRβ gene expression in the fibromuscular stroma (p < 0.001)." (PMID 35530322, 2022). "Immunofluorescence staining of PDGFRB showed that pericytes had a perivascular location and confirmed that pericytes were enriched in tumor samples." (PMID 35664061, 2022). "Sorafenib (Nexavar ®) is an orally available ATP-competitive inhibitor of Raf kinase with activity against other kinases, such as BRAF, VEGFR-2 and -3, and PDGFRβ, to impede tumor growth and angiogenesis in vivo." (PMID 35957881, 2022). "A tissue analysis subsequently demonstrated co-localization of the nanobody with PDGFRB expression in the tumour stroma." (PMID 36139509, 2022). "As seen in the immunohistochemistry staining of PDGFRB in peritoneal metastases, PDGFRB expression is mainly localized in the tumour stroma." (PMID 36139509, 2022). "Future work should assess the merits and disadvantages of the various PDGFRB-targeting platforms (affibody, nanobody, small molecule, etc.)in terms of pharmacokinetics, binding affinities and specificities, and tumour tissue retention." (PMID 36139509, 2022). "Within the tumor vasculature specifically, PDGFRβ-positive cells wrapped around CD31-positive cells, consistent with the expected localization and function of pericytes." (PMID 36192379, 2022). "Blocking PDGFRβ kinase activity with imatinib effectively reduces tumor burden and prolongs survival, although the downstream molecular mechanisms remain elusive." (PMID 36045346, 2022). "Upon tumor recurrence (after the discontinuation of denosumab treatment) the intensity of PDGFRβ immunostaining in stromal/tumor cells was restored/decreased." (PMID 36091939, 2022). "Levels of additional CAF markers such as fibroblast activation protein (FAP) in MH6419 tumours and PDGFRβ in B16F10 tumours were also significantly reduced in Atf4Δ/Δ mice." (PMID 35654839, 2022).